TLR2 (toll like receptor 2)
Diseases named in the same sentence as TLR2 in open-access papers (continued):
Sharing a sentence is not in itself a finding about the gene and the disease.
breast carcinoma (continued). "In this review, we present a comprehensive overview of the role of TLR2 and STING in breast cancer, and we explore the potential to target these PRRs for drug development." (PMID 38203626, 2023). "In particular, several studies showed that the Toll-like receptor 2 (TLR2) and the cyclic GMP–AMP synthase (cGAS)–stimulator of interferon genes (STING) pathways play a central role in breast cancer progression." (PMID 38203626, 2023). "TLR2, TLR3, and TLR4 as biomarkers of proinflammatory response were increased significantly in patients with inflammatory bowel disease and breast cancer." (PMID 35425840, 2022). "A mouse mammary tumor model of ferroptosis verified SAPE-OOH and TLR2 as critical players in the clearance of ferroptotic cells in vivo." (PMID 33432112, 2021). "The inhibition of TLR2 or its downstream targets CD14, MyD88, and IRAK1 can inhibit the proliferation of human breast cancer (BRCA) cells." (PMID 33138076, 2020). "OM-174 a TLR-2/4 agonist together with BCG demonstrated anti-cancer activity through induction of TNF-α, whilst krestin, a selective TLR-2 agonist, inhibits breast cancer in mice." (PMID 29588627, 2018). "We initially performed a broad analysis on TLR and TLR2/4 co-receptor (CD14 and MD2) mRNA expression patterns in various breast cancer cell lines." (PMID 26392082, 2015). "This has been observed with Toll-like receptor 2 (TLR2), TLR4 and TLR9 agonists, such as BCG and paclitaxel, which have demonstrated significant benefit for the treatment of bladder and breast cancers." (PMID 23547558, 2013). "For examples, Gram-positive bacterium Listeria monocytogene accelerated mouse hepatocarcinoma cell H22 growth via TLR2 signaling; TLR9 agonist CpG ODN promotes breast cancer cell MDA-MB-231 to activation of invasion via increased MMP9 secretion." (PMID 20520770, 2010). "TLR2 and HMGB1 correlate with breast cancer progression and poor prognosis." (PMID 40727252, 2025). "Analysis of TCGA data reveals significant involvement of TLR2, TLR1, and TLR6 in breast cancer." (PMID 38903515, 2024). "Moreover, polysaccharide krestin (PSK), the natural ligand of TLR2, stimulates TLR2 and induces NK cell-mediated antitumor activity in HER2+ breast cancer cells." (PMID 38903515, 2024). "TLR2/4 are dominant in gastrointestinal cancers, like esophageal cancer, GC, and colon cancer, while TLR9 signaling is more common in other kinds of cancers, like breast cancer, prostate cancer, and renal cell carcinoma." (PMID 37153547, 2023). "Apart from its direct effect on tumorigenesis, we have demonstrated that TLR2 mediates breast cancer resistance to doxorubicin and other drugs, inducing immunogenic cell death (ICD) and the release of DAMPs that activate TLR2 signaling in cancer cells, thereby enhancing their survival." (PMID 38203626, 2023). "A significant increase in the levels of soluble TLR2 was observed in the sera from patients with both metastatic and non-metastatic breast cancer, as compared with healthy donors." (PMID 38203626, 2023). "In the case of TLR-2 and HVEM, the median plasma levels of these two biomarkers were significantly lower in early breast cancer patients compared to those of healthy controls these being 24059.42 vs. 30477.20 pg/mL, p<0.0141 and 1866.92 vs. 2290.19 pg/mL, p<0.0001, respectively." (PMID 35677046, 2022). "The previous studies showed that clinical use of proinflammatory markers (TLR2, TLR2, TLR4, TNF-α, sTNFR-1, and sTNFR-2) provided a means of evaluating inflammatory diseases such as inflammatory bowel disease, breast cancer, coronary artery disease, chronic heart failure, and type 2 diabetes." (PMID 35425840, 2022). "Furthermore, it has been observed that human breast cancer cell-derived exosomes induce the secretion of IL-6, TNFα, and CCL2 from both human THP-1 and murine RAW macrophage cell lines via the toll-like receptor 2/NF-κB signaling pathway." (PMID 29867925, 2018).
breast carcinoma (continued). "Our results showed that knockdown of TLR2 markedly reduced the invasive capacity of highly metastatic cancer cell lines, including human lung adenocarcinoma A549 cells and human breast cancer MDA-MB-231 cells (data not shown)." (PMID 23866094, 2013). "Also, adenovirus staining colocalized with TLR9 in endosomes and with TLR2 on the cell surface indicating that in this breast cancer cell type TLR9 and TLR2 are active in virus recognition." (PMID 21079774, 2010). "Mechanistically, SLC12A8 activated the TLR signaling pathway (upregulating TLR2, MyD88, IRAK1, TAK1 in CD8+ T cells), leading to increased PD-1 expression on CD8+ T cells, resulting in their functional exhaustion and enhanced invasive ability of Luminal B breast cancer cells." (PMID 41795804, 2026). "Engagement of pattern recognition receptors such as TLR2 (for LTA) and TLR4 (for LPS) may play a central role, consistent with studies in cardiomyocytes, intestinal epithelial cells, and breast cancer lines showing that TLR activation modulates DOX uptake and toxicity." (PMID 41156777, 2025). "Of note, soluble TLR2 was significantly higher in metastatic than in non-metastatic breast cancer patients, suggesting that TLR2 might be used as a biomarker to monitor disease progression." (PMID 38203626, 2023). "Furthermore, stimulation with Pam3CSK4, a TLR2/1 agonist, does not lead to a more effective anti-tumor activity in organotypic brain-slice ex vivo co-cultures of any breast cancer model." (PMID 36224342, 2022). "Indeed, scoring of membrane TLR4 expression in breast cancer lesions did not reveal as much as that of cytoplasmic staining, and both TLR2 and TLR4 have been reported to be expressed intracellularly as well." (PMID 26392082, 2015). "In contrast, our findings show that TLRs (TLR2, TLR 3, TLR 4) are preferentially expressed in TN breast cancer cell lines with constitutive NFκB activity, suggesting that the TLRs may be responsible for the NFκB activation pathway rather than induced by the same." (PMID 26392082, 2015). "For example, TLR2 signaling has been shown to promote lung cancer cell growth and resistant of apoptosis; TLR3 can directly trigger apoptosis in human cancer cells, such as breast cancer cells, TLR2 and TLR9 can promote invasiveness and metastasis through metalloproteases and integrins." (PMID 20618976, 2010). "Moreover we recently showed a cell-intrinsic role for the TLR2/MyD88 pathway in breast and colon epithelial stem/progenitor cell populations, and similar to what we describe here in HNSCC, the inhibition of the TLR2 signaling pathway in breast cancer resulted significant growth inhibition." (PMID 25846753, 2015). "In contrast, breast cancer CD44+/CD24−/low CIC have dysregulated innate immune responses featuring dysfunctional virus recognition caused by impaired trafficking of TLR9 and cofactor MyD88 and the absence of TLR2, having a deleterious impact on TLR pattern recognition receptor signaling." (PMID 21079774, 2010). "Compared to TLR2/4, clarified reports about the interaction of TLR9 with HMGB1 in breast cancer is still absent." (PMID 35637945, 2022). "In conclusion, non-CIC breast cancer cells feature oncolytic adenovirus recognition by TLR9 and TLR2 and intact TLR trafficking, whereas CIC have defects in trafficking of TLR9 and co-factor MyD88 and lack of TLR2." (PMID 21079774, 2010).
acne (63 papers, 2009 to 2026). An inflammatory process of the sebaceous glands which is characterized by comedones, nodules, papules and/or pustules on the skin. "In vivo, the genes encoding CXCL8, TLR2, and β-defensin-4 have been shown to be upregulated in acne lesions, together with NF-κB and AP-1, suggesting an activation of TLR2 by P. acnes." (PMID 27902761, 2016). "Based on this study, the calcium ion concentration corresponding to TLR2 expression level could be used as a new diagnostic index for examining the severity of acne." (PMID 39588538, 2024). "This is supported by the high degree of association between HylA and HylB with clinical disease or health, their TLR2 dependency in immunopathologic mechanisms, consistent with acne vulgaris, and the contribution of the two Hyl variants to immunopathology and health." (PMID 38052825, 2023). "In addition, TLR2 Arg753Gln polymorphism carriers were found to have an increased risk for acne vulgaris in Chinese Han patients." (PMID 27031066, 2016). "Therefore, the investigation with downregulation of TLR2 signaling pathway activated with P. acnes or PGN is needed to determine if micro-current stimulation can improve the inflammatory response associated with acne." (PMID 35269651, 2022). "Cutibacterium acnes, a major skin commensal bacterium, induces inflammatory cytokine production in keratinocytes through Toll-like receptor 2 (TLR2) signaling and contributes to acne vulgaris pathogenesis." (PMID 41753736, 2026). "TLR2 has been shown to be highly expressed on perifollicular and peribulbar macrophages in acne lesions, and then in activation of the signaling cascade NLRP3 inflammasome, NF-kB and MAPK signalling pathways." (PMID 41010653, 2025). "Research has found that Propionibacterium acnes induces acne inflammation mainly through a member of TLRs-TLR2." (PMID 38371936, 2024). "In this study, we observed that keratinocytes secreted IL-6 and MCP-1 during acne induction through a TLR2-calcium-related signaling mechanism distinct from that of macrophages." (PMID 39588538, 2024). "Elevated IL-17, IL-23, and TNFα levels in acne lesions, coupled with TLR2(+) macrophages and IL-17 cells, reveal a complex network of inflammatory pathways that exacerbate acne severity." (PMID 38791344, 2024). "In acne lesions, the presence of biofilm-derived C. acnes activates miR-146a, TLR2 and its downstream pathways in keratinocytes." (PMID 37344849, 2023). "C. acnes initiates the inflammatory process of acne pathogenesis by triggering the production of ROS and inflammatory cytokines via Toll-like receptor 2, peroxisome proliferator-activated receptor, the mTOR pathway, and the innate immune system." (PMID 37514071, 2023). "Second, C. acnes engages TLR2, a signaling molecule highly activated in acne lesions, and elicits inflammation in keratinocytes, sebocytes, and monocytes, thereby facilitating acne development." (PMID 37344849, 2023). "The inflammatory response produced in acne is mediated through the detection of the C. acnes-pathogen-associated molecular patterns (PAMP), mainly peptidoglycan and lipoteichoic acid, by TLR2 and TLR4." (PMID 37232724, 2023). "The potential importance of Hyl in humans is further advanced by linking Hyl mechanisms and acne through their TLR2 dependence." (PMID 38052825, 2023). "This probably explains why a higher efficacy to TLR2-targeted drugs, such as topical retinoids, was observed in patients with a more severe form of acne." (PMID 35329904, 2022). "Toll-like receptors (TLRs) are critical in regulating the innate immune response to pathogens in skin, and TLR-2 signaling has been shown to play a key role in the pathogenesis of several dermatological conditions including acne." (PMID 35056807, 2022). "It was also showed that, as acne was aggravated, the cells demonstrated an increased expression of TLR2." (PMID 35329904, 2022).
acne (continued). "It was found that the expression of TLR2 was more intense in pilosebaceous units and skin infiltrations in areas of inflammatory lesions and severe acne lesions." (PMID 35329904, 2022). "There are many reports that C. acnes contributes to the production of cytokines that are pivotal in inflammatory acne via a TLR2 pathway." (PMID 36437519, 2022). "The inflammatory response to the recognition of P. acnes in TLR2 contributes to the inflammatory nature of acne by inducing monocytes to secrete pro-inflammatory cytokines including TNF-α, IL-1, and IL-8." (PMID 35269651, 2022). "It is suspected that, in the course of inflammatory acne, C. acnes activates cells by interactions with TLR2 and TLR4." (PMID 35329904, 2022). "In the interaction between TLR2 and P. acnes, NF-κB acts as an essential TLR2 downstream signal that has a major impact on inflammatory responses in acne by releasing various pro-inflammatory cytokines such as COX-2, iNOS, IL-1β, and TNF-α." (PMID 35269651, 2022). "The secretion of interleukin 1α (IL-1α) via activation of Toll-like receptor 2 (TLR2) by ligands present on C. acnes can be detected in inflammatory acne vulgaris." (PMID 34867837, 2021). "A previous study showed that the aryl hydrocarbon receptor promotes secretion of inflammatory factors TNF-α and IL-8 in human SZ95 sebocytes, which indicates a possible mechanism in TLR2-mediated acne." (PMID 32685503, 2020). "Briefly, virulent C. acnes type IA in acne pathogenesis activates mainly TLR2 in keratinocytes, sebocytes, monocytes and macrophages, which induce an inflammatory response with activation of the NF-κB pathway and produce ROS." (PMID 33171837, 2020). "C. acnes contribute to the inflammation in acne through activation of toll-like receptors (TLRs), in particular, TLR-2." (PMID 32373312, 2020). "Zinc salts and systemic isotretinoin are effective against inflammatory acne via reduction in TLR2 expression in human keratinocytes." (PMID 30120655, 2019). "In acne lesions, TLR2-expressing macrophages surround pilosebaceous follicles, and P. acnes induces cytokine production by monocytes via TLR2." (PMID 30987239, 2019). "Studies have shown a direct effect of P. acnes on keratinocytes via interaction with TLR2 that induces the production of various inflammatory cytokines, thereby promoting acne inflammation." (PMID 30120655, 2019). "TLR2 have been found to be largely expressed in peribulbar and perifollicular macrophages in acne lesions, and TLR2-expressing cells have a correlation with the acne lesions." (PMID 31319552, 2019). "Our data also put forward the need to revisit the role for the P. acnes–TLR2 pathway and to reveal the TLR2 independent effects of P. acnes as well, which could provide clues to understand the exclusive pathogenic features of P. acnes in the pathogenesis of acne." (PMID 29927962, 2018). "In clinical acne samples, P. acnes triggers activation of TLR-2 which modulates production of inflammatory cytokines, including TNF-α, IL-1β, IL-6, and IL-87,30." (PMID 29507345, 2018). "Biopsies of acne lesions also show abundant TLR2 expression on the surface of macrophages surrounding pilosebaceous follicles." (PMID 30285861, 2018). "ATRA treatment decreased TLR2 levels in monocytes isolated from both healthy donors and acne patients following isotretinoin therapy, although TLR4 expression was not affected." (PMID 30319618, 2018). "TLR2 bacterial ligands present on C. acnes have been proposed to promote inflammation in acne, stimulating interleukin-1alpha (IL-1α), and granulocyte macrophage-colony stimulating factor (GM-CSF) release." (PMID 30285861, 2018). "P. acnes contributes to the inflammatory lesions of acne by activating innate immunity via the TLR2 expressed on cutaneous cells." (PMID 27902761, 2016). "The surface proteins of P. acnes involved in the activation of TLR2 on keratinocytes and monocytes and leading to inflammatory lesions in acne have yet to be identified." (PMID 27902761, 2016).
acne (continued). "It is known that P. acnes contributes to inflammation in acne through activation of the toll-like receptors (TLRs), especially TLR2." (PMID 26197393, 2015). "A key factor involved in the pathophysiology of acne vulgaris is the presence of P. acnes, which triggers inflammation in acne sufferers through activation of the innate immune receptor TLR2 on keratinocytes." (PMID 26197393, 2015). "The importance of TLR-mediated immune response is supported by the presence of TLR2 expressing cells in inflammatory acne lesions." (PMID 25153527, 2014). "As the treatment of NHEK with LTA and PGN was reported to trigger NFκB activation via TLR2, in turn regulating the release of the potent chemokine IL-8, it is rational to investigate the role of PAMPs in the pathogenesis of acne." (PMID 24011352, 2013). "An increase in the expression of both TLR2 and TLR4 was also demonstrated in keratinocytes and associated with the initial inflammatory process observed in acne lesions." (PMID 22448280, 2012). "TLR2 activation leads to a triggering of the transcription nuclear factor and thus the production of cytokines/chemokines, phenomena observed in acne lesions." (PMID 20981308, 2010). "Pilosebaceous follicles in acne lesions are surrounded by macrophages expressing TLR2 on their surface." (PMID 20981308, 2010). "TLR-2, present at the surface of keratinocytes, is upregulated in acne lesions and is potentially involved in the recognition of P. acnes during the inflammatory process." (PMID 19629174, 2009). "The TLR2/NF-κB pathway is highly expressed in acne vulgaris." (PMID 40507073, 2025). "This suggests that reduced TLR2 expression may be an important mechanism in the treatment of acne with isotretinoin." (PMID 41010653, 2025). "TLRs like TLR-2 can be found in macrophages and keratinocytes within the follicle and can contribute to acne pathogenesis; TLR-4 activity may also contribute to acne pathophysiology." (PMID 38534705, 2024). "C. acnes also induces TLR2 and TLR4 on keratinocytes, a mechanism that could play an essential role in acne-linked inflammation as TLR2 activation drives an inflammatory transcriptional program in Th17 cells." (PMID 37998335, 2023). "The TLR2 dependence of acne vulgaris is a well-recognized feature of the skin disease." (PMID 38052825, 2023). "While the pathogenesis of acne has yet to be fully understood, the Gram-positive bacterium Cutibacterium acnes (C. acnes) has been identified as a key player for this inflammatory skin condition and activation of TLR-2 by C. acnes has been reported to trigger inflammatory cytokine responses in acne." (PMID 35056807, 2022). "However, there is a limit to concluding that the inflammatory response mediated by TLR2, one of the main mechanisms of acne, can be directly controlled from the results of peripheral blood analysis alone." (PMID 35269651, 2022). "Indeed, the macrophages distributed around acne lesions produce pro-inflammatory cytokines as a result of TLR-2 activation by P. acnes." (PMID 35269651, 2022). "Therefore, research focused on TLR2 provides valuable information on new therapeutic targets of acne vulgaris." (PMID 35329904, 2022). "P. acnes plays a crucial role in the inflammatory phase of acne through activating innate immunity via toll-like receptor 2 (TLR2), one member of transmembrane proteins that respond to particular pathogen-associated molecular patterns (PAMPs) such as bacterial cell wall components." (PMID 35269651, 2022). "Thus, AMPs can be potential candidate for treating acne vulgaris and some of them are reported to show treatment potential for acne vulgaris by direct killing bacteria and inhibiting Toll-like receptor 2 (TLR2)-induced NF-κB activation." (PMID 34955858, 2021). "All this data supports the idea that the TLR2 of different skin cell types, such as keratinocytes, sebocytes and immune cells, is highly involved in C. acnes recognition and inflammation initiation in acne." (PMID 33171837, 2020).